SETD1A (SET domain containing 1A, histone lysine methyltransferase)
Diseases named in the same sentence as SETD1A in open-access papers (continued):
Sharing a sentence is not in itself a finding about the gene and the disease.
tumor (continued). "In particular, inhibition of SETD1A, a histone methyltransferase involved in H3K4 methylation, has been shown to suppress tumor growth and metastasis in vivo." (PMID 41255580, 2025). "The tumor cells (CAOV3, SKOV3, RMGI, OVCAR5 and OVCAR8) expressed high levels of SETD1A compared with normal epithelial cell IOSE80." (PMID 36707804, 2023). "Downregulated SETD1A in BGC‐823 cells markedly inhibited tumor growth and reduced tumor weight." (PMID 32291851, 2020). "In the current study, we discovered that the expression of SETD1A was higher in GC tumor specimens compared to surrounding nontumor tissues." (PMID 32291851, 2020). "Our data, however, demonstrate that SETD1A is not required for overall maintenance of H3K4 methylation in tumour cells, suggesting that SETD1A activity is dependent on the cellular context." (PMID 26394836, 2015). "Therefore, we speculate that SETD1A may promote HCC stemness through depositing H3K4me3 on the promoters of oncogenes and H3K27me3 on the promoters the tumor suppressor genes." (PMID 37581938, 2023). "Similarly, the increase in SETD1A expression in tamoxifen-resistant cells seems to be the result of the dominant survival of resistant clones, CSCs, expressing high levels of SETD1A and SOX2 due to intra-tumor heterogeneity in primary BC." (PMID 35966598, 2022). "In addition, SETD1A is essential for the expression of stem cell factor (e.g., OCT4, octamer-binding transcription factor 4) and stem cell formation in mCRPC, suggesting the importance of SETD1A expression in mCRPC tumor formation." (PMID 32629770, 2020).
neurodevelopmental disorder (19 papers, 2018 to 2026). A behavioral and cognitive disorder with onset during the developmental period that involves impaired or aberrant development of intellectual, motor, or social functions. "Exome sequencing identified two variants: one in the SETD1A gene, associated with neurodevelopmental disorders, and another in NLRP12, previously reported as benign." (PMID 42157874, 2026). "Rare SCZ risk mutations, including premature open reading frame (ORF) termination variants in SETD1A, are also associated with intellectual disability, autism, and other neurodevelopmental disorders (NDD)." (PMID 40962831, 2025). "Furthermore, well-known risk factors for neurodevelopmental disorders, Chd8 and Setd1a (ChIP-Atlas, Neural type, FE>1), were also identified in the E16-specific DHSs." (PMID 40501413, 2025). "Future multi-modality functional assay of neurons carrying SETD1A LoF mutations especially in the context of other neurodevelopmental disorder risk genes on a large scale will further establish the functional role of SETD1A in contributing to neuropsychiatric and neurodevelopmental disorders." (PMID 40962831, 2025). "In addition to SRRM2 and PNN, we tested SETD1A—a histone methyltransferase implicated in neurodevelopmental disorders that contains 24 consecutive serines—and observed enrichment in tau aggregates." (PMID 36626563, 2023). "Four of the 18 high confidence variants (in ERF, SETD1A, SHANK3 and ZBTB18) were recurrent, with these variants having been reported previously in individuals with neurodevelopmental disorders." (PMID 36117209, 2023). "In addition, mutations in the SETD1A gene have been reported to be associated with early-onset seizures, which may be related to the fact that the expression of USP39 is reduced by the regulation of the mutant SETD1A gene, which in turn leads to neurodevelopmental disorders." (PMID 40990019, 2025). "Setd1a may also have a role in regulating the balance between neuronal progenitor cells (NPC) proliferation and differentiation in neurogenesis, suggesting that perturbations to this balance may play a role in pathogenic mechanisms of Setd1a LoF in neurodevelopmental disorders." (PMID 39141687, 2024). "A significant number of these genes (CHD3, SETD1A, KAT6A, SETBP1, TNRC6B, ZFHX4, ARID1A and TRIO) have been associated with neurodevelopmental disorders with or without speech problems." (PMID 29463886, 2019).
neurological disorders (2 papers, 2021 to 2025). "Studying mouse models for SETD1A deficiency has recently provided important information about the etiology of SETD1A associated neurological disorders." (PMID 34803610, 2021). "Interestingly, SETD1A and the STX1B distal target are both associated with neurological disorders, while the HSD3DB7 and STX4 distal targets are associated with immune-related and cardiometabolic diseases, respectively." (PMID 39727170, 2025). "Insight into the specific molecular and cellular (neuronal) mechanisms affected by LoF of SETD1A will shed more light on how neurological disorders might be established in the brain." (PMID 34803610, 2021).
prostate (1 paper, 2020). "Overexpression of SETD1A was significantly correlated with overexpression of FOXM1 (GSE50936, GSE70769) and low survival rates of prostate patients (GSE40272)." (PMID 32629770, 2020).
SETD1A also shares sentences with these, for which no sentence is quoted: infection (5 papers); autism (4); psychiatric disorder (4); cyst (3); Hyperglycemia (3); lobular breast cancer (3); autism spectrum disorder (2); breast tumors (2); congenital heart disease (2); Kabuki syndrome (2); liver cancer (2); lung adenocarcinoma (2); acute lymphocytic leukaemia (1); albinism (1); apraxia (1); cholestasis (1); ciliopathies (1); cognitive decline (1); coloboma (1); Cornelia de Lange syndrome (1); esophagus cancer (1); Fanconi anemia (1); fibrosis (1); follicular lymphoma (1); generalized epilepsy (1); genetic diseases (1); head and neck squamous cell carcinoma (1); heart disease (1); hepatitis C (1); hyperlipidemia (1).
A further 24 diseases each share a sentence with SETD1A in 1 paper.